NOTCH4 (notch receptor 4)
Diseases named in the same sentence as NOTCH4 in open-access papers (continued):
Sharing a sentence is not in itself a finding about the gene and the disease.
breast cancer (continued). "Notch receptors have been shown to be important for the formation of spontaneous mammary tumors in vivo after overexpression of constitutive, active forms of Notch1 or Notch4." (PMID 24919951, 2014). "Our data suggest that targeting Notch4 and Nicastrin is a potential approach to reverse endocrine resistance in breast cancer patients." (PMID 24919951, 2014). "Although most studies have been utilized Notch1 as the readout of Notch signaling, the four Notch receptors, Notch1, Notch2, Notch3 and Notch4, are thought to have different functions in breast cancer." (PMID 25229616, 2014). "Knockdown of Notch1 or Notch4 inhibited self-renewal and tumorsphere forming ability of breast cancer cells, supporting their roles for the maintenance of cancer stem cells." (PMID 25229616, 2014). "In vivo knockdown experiments of Notch 1 and Notch 4 in tumour-bearing mice showed that the tumour size decreased and there was a reduction of breast cancer recurrence in these mice." (PMID 24599057, 2014). "Expression of Notch receptors and ligands has been described in a wide variety of different tumor types, such as colorectal, prostate, liver, pancreatic and breast cancer and a role for Notch4 in regulating breast cancer stem cell activity has been proposed." (PMID 23601498, 2013). "Taken together, our results show that Notch4 expression is upregulated in the tumor vasculature in both murine and human mammary tumors, suggesting a possible role for this receptor in breast cancer formation and angiogenesis." (PMID 23601498, 2013). "We also examined NOTCH1 and NOTCH4 expression because of their role in mouse breast cancer malignancy and their overexpression in triple-negative breast cancer subtypes." (PMID 23826634, 2013). "Here, we show that Notch4 expression is required for tumor onset and early tumor perfusion in a mouse model of breast cancer." (PMID 23601498, 2013). "In both the normal mammary gland and breast cancer, Notch4 signaling maintains an undifferentiated, stem/progenitor-like state." (PMID 23593654, 2013). "Reports from others demonstrate that Notch4 signaling is elevated in CD44+/CD24− cells and that inhibiting this pathway reduces mammosphere formation and prevents tumor initiation in vivo identifying Notch4 as a critical regulator of breast cancer TICs." (PMID 23593654, 2013). "In this study we demonstrate that Notch4 expression is upregulated in the vasculature of mammary tumors." (PMID 23601498, 2013). "Our results suggest a novel role for Notch4 in the establishment of tumor colonies and vessel perfusion of transplanted mammary tumors." (PMID 23601498, 2013). "Our study demonstrates Notch4 upregulation in the vasculature of both mouse models of mammary adenocarcinoma and human breast cancer." (PMID 23601498, 2013). "It is possible that different types and grades of breast carcinoma present different Notch4 expression levels and distribution." (PMID 23601498, 2013). "Changes in Notch4 are of particular interest because previous studies have shown that blocking NOTCH4 receptor activity inhibits tumor formation of xenografted breast cancer cells, whereas blocking NOTCH1 has less of an effect." (PMID 22225988, 2012). "Overexpression of constitutively active forms of Notch-1, Notch-3, and Notch-4 develop spontaneous murine mammary tumours in vivo." (PMID 21847123, 2011). "By contrast, mouse mammary tumors resulting from activated Notch4 show activated Mek and Akt and a synergistic relationship between Notch and the Ras signalling pathway has been proposed." (PMID 18950493, 2008). "Increased NOTCH1 and NOTCH4 expressions have been observed in breast cancer." (PMID 41561443, 2026). "NOTCH4 has a role in breast cancer through its involvement in angiogenesis and vascularization, which may influence tumor progression and metastasis." (PMID 41561443, 2026).
breast cancer (continued). "It is reported that the Notch receptor Notch-4 plays a primary role in EMT signaling in breast cancer cells and could be a potential target." (PMID 41211430, 2025). "We found that Notch4 is expressed by the tumor endothelium in multiple types of tumors, which is supported by analysis of publicly available single-cell sequencing, which shows that Notch4 is significantly enriched in ECs across multiple subtypes of human breast cancer." (PMID 38984877, 2024). "In ER+ breast cancer, Notch4 increases breast cancer stem cell activation and endocrine therapy resistance, proposing that Notch4 inhibition will overcome endocrine therapy resistance and decrease recurrence in ER+ breast cancer." (PMID 37149651, 2023). "As expected, the knockdown of Notch4 expression in TNBC cells enhanced Vimentin expression, a mesenchymal status marker, and E-cadherin expression, an epithelial status marker, indicating that depletion of Notch4 expression in TNBC cells boosted breast cancer metastasis." (PMID 37149651, 2023). "In addition, increased Notch4-Hey1 mRNA expression and decreased patient survival were found to be correlated in another study, confirming Hey1 as a marker for breast cancer development." (PMID 38007419, 2023). "We showed that Notch1 can activate ERα-dependent transcription in the absence of estrogen, evading estrogen deprivation and that Protein Kinase C (PKC)α, a known marker of endocrine resistance, induces endocrine resistance in HR-positive breast cancer cells via Notch4." (PMID 37568775, 2023). "However, the knockdown of Notch4 shifted the spindle-shaped morphology to cobblestone-like morphology, suggesting that Notch4 depletion inhibited breast cancer metastasis." (PMID 37149651, 2023). "In this regard, it is worth mentioning that NOTCH4 appears to be the most important NOTCH gene for inhibiting breast cancer growth, since the overexpression of NOTCH4 increases, whereas the inhibition of NOTCH4 reduces, the proliferation and invasiveness of triple-negative breast cancer cells." (PMID 35163478, 2022). "In contrast, Notch4 has been considered to act as a carcinogen in breast cancer." (PMID 36139447, 2022). "As the NOTCH4 signal pathway is found to be enriched in the Her2 subtype in our study, using NOTCH4 antagonists to suppress NOTCH4 signaling may be a novel and individually distinct strategy to treat Her2 subtype breast cancer." (PMID 36313438, 2022). "However, in our earlier work, which focused on the closely related protein Notch4, immuno-staining for Notch1 protein in Breast cancer cell lines-SUM149, Hs578T and HCC1806, showed that NIC1 was excluded from the nucleolus." (PMID 36211456, 2022). "Interestingly, PKCα/Notch4 crosstalk has also been identified in endocrine therapy resistant ER+ breast cancers." (PMID 34295896, 2021). "Activation of JAG1/Notch4 signalling was sufficient to induce endocrine therapy resistance in MCF-7 cells, and tamoxifen resistance could be predicted for in ER+ breast cancer patients using a Notch4/HES/Hey gene signature." (PMID 34295896, 2021). "Moreover, mutational disruption of ERα ligand-binding domain (which frequently occurs in therapy-resistant ER+ breast cancers patients) promoted the acquisition of a stem-cell-like phenotype and the upregulation of the Notch4 signaling pathway." (PMID 34680255, 2021). "Notably, although activation of Notch2 induced higher vascularization, the vessels were smaller and comprised a more immature network as compared with Notch4-activated signaling, suggesting its suppressive role in the angiogenesis of breast cancer." (PMID 33919109, 2021). "In vivo, transgenic mice which exhibit a constitutively active variant of Notch4 do not develop normal mammary glands and instead develop mammary tumors." (PMID 34587981, 2021). "Notch1 and Notch4 have been validated to regulate breast cancer stem cells by recent studies." (PMID 32636747, 2020).
breast cancer (continued). "We then performed immunohistochemistry staining of NOTCH4 in patients' breast tumors and corresponding para-tumor tissues and revealed that NOTCH4 was highly expressed in tumors compared with para-tumor tissues, demonstrating the dysregulated expression of NOTCH4 in breast cancer." (PMID 32104513, 2020). "Clementz and colleagues (2011) demonstrated NOTCH1 and NOTCH4 are transcriptionally activated by PEA3 in breast cancer cell lines, and knockdown of PEA3 or treatment with a GSI resulted in a G1 cell cycle arrest, increased apoptosis, and either treatment reduced tumor burden in mice." (PMID 33003540, 2020). "Their finding verified that Notch4 may produce more robust effect in maintaining breast cancer stemness." (PMID 32636747, 2020). "Therefore, all of these studies suggest that DLL4 and Notch 4 are viable therapeutic targets for both triple negative and ER+ breast cancer treatment." (PMID 30975104, 2019). "The purpose of this up-to-date review is to provide a detailed overview of the specific role of all four Notch receptors (Notch1, Notch2, Notch3, and Notch4) in TNBCs, thus identifying the Notch signaling pathway deregulation/activation as a pathognomonic feature of this breast cancer subtype." (PMID 31379945, 2019). "Moreover, Wang and colleagues analyzed a wider panel of breast cancers (98 samples) in which TNBCs exhibited the highest Notch4 expression, thus suggesting a pivotal role of Notch4 receptor in this subtype." (PMID 31379945, 2019). "The levels of NICD and Hes1 were elevated in all samples, suggesting that breast cancer may be promoted by dysregulation of Notch signaling and that Notch-4 is directly involved in the regulation of DCIS mammosphere formation and/or growth." (PMID 30111989, 2018). "Moreover, Notch4 is a crucial mediator of endocrine therapy resistance in models of luminal breast cancers." (PMID 30515368, 2018). "Additionally, truncated human Notch4/Int3 (activated Notch4) instigated mammary tumors, through transcription of RBP-jk and ANK repeats." (PMID 30515368, 2018). "Withaferin-A-mediated inhibition of MDA-MB-231 cell migration was significantly augmented by knockdown of Notch-2 and Notch-4 protein, suggesting that the Notch-2 and Notch-4 activation by withaferin-A impairs its inhibitory effect on breast cancer cell migration." (PMID 26959007, 2016). "Thus, we establish that BCSC and NOTCH4 activities predict both de novo and acquired tamoxifen resistance and that combining endocrine therapy with targeting JAG1-NOTCH4 overcomes resistance in human breast cancers." (PMID 26387946, 2015). "Moreover, expression data from publically available breast cancer patient dataset demonstrate that Notch4 expression significantly correlates with several markers of EMT transition." (PMID 24919951, 2014). "Finally, we found a positive correlation between Notch4 expression and post-progression survival in ERα-positive breast cancer patients." (PMID 24919951, 2014). "To unravel the role of Notch4 in tumor angiogenesis, we chose breast cancer as a solid tumor model." (PMID 23601498, 2013). "However, in our study, our mouse model provides evidence that host, likely vascular, Notch4 plays a role in breast cancer development." (PMID 23601498, 2013). "We found that Notch4 expression is upregulated in mouse and human mammary tumor vasculature." (PMID 23601498, 2013). "We examined the requirement for Notch4 in the development of breast cancer vasculature." (PMID 23601498, 2013). "To test the hypothesis that Notch4 is involved in pathological angiogenesis, we used mammary tumors as a model." (PMID 23601498, 2013). "Orthotopic transplantation of mouse mammary tumor cells wild type for Notch4 into Notch4 deficient hosts enabled us to delineate the contribution of host Notch4 independent of its function in the tumor cell compartment." (PMID 23601498, 2013).
breast cancer (continued). "In contrast to the more differentiated breast cancer cell lines, Notch4 was readily detectable in the ES cells, whereas Notch3 expression levels were difficult to detect, reflecting the known expression patterns and functional roles of these two genes in differentiation and development." (PMID 23863842, 2013). "Thus, its possible that NOTCH4 is the relevant NOTCH receptor in human breast cancer-initiating cells." (PMID 22992387, 2012). "Notably, a recent study demonstrated reduced stem cell activity in response to Notch1 or Notch4 suppression using the same breast cancer cell lines described herein, which supports the use of gamma-secretase inhibitors in clinical trials." (PMID 21914219, 2011). "We identified 7 genes (ITGB1, SNAI1, NOTCH4, STAT5B, RAPGEF3, LAMA2, and GNAI1) that have been implicated in both stemness and the drug response and validated their relevance through an analysis of data from breast cancer patients in the TCGA database using UCSC Xena." (PMID 39180549, 2024). "Investigations on the association of NOTCH1 rs3124591, NOTCH3 rs1043994, and NOTCH4 rs3830041 with the risk of human cancers are rare, however, several studies have shown a link between NOTCH2 related rs11249433 and increased risk of breast cancer especially in women of European ancestry." (PMID 34257585, 2021). "The Notch signaling system that contains four Notch receptors (Notch1- Notch4) and five canonical ligands (Dll1, Dll3, Dll4, Jagged1 and Jagged2), plays important roles including carcinogenesis, cancer stem cell renewal, angiogenesis, and chemotherapy resistance in the progression of breast cancer." (PMID 33413403, 2021). "Moreover, JAG1, a ligand for Notch receptor, was previously found to be upregulated in drug-resistant breast cancer cells, and this CSC-driven drug resistance in ER+ breast cancer was correlated to the interaction of JAG1 and NOTCH4 in association with the Notch signaling pathway." (PMID 33919109, 2021). "However, probably due to the relatively low endogenous NOTCH4 mRNA level in breast cancer, we could only achieve a partial knockdown efficiency." (PMID 32104513, 2020). "Interestingly, transgenic expression of Notch4 NICD caused mammary tumors in the absence of RBP-jk in mice harboring conditional knockout of RBP-jk." (PMID 30515368, 2018). "Taken together, our study demonstrates that CLPs of luminal A breast cancer cells can be induced to differentiate to a more benign phenotype in conjunction with their microenvironment by promoting downstream signaling that emanates from Int-αvβ3, such as inhibition of Notch4 signaling." (PMID 27906177, 2016). "We first assessed whether an orthotopic tumor model derived from the MMTV-PyMT (polyomamiddleTantigen driven by the mouse mammary tumor virus LTR) transgenic mouse line is a valid experimental tool to study the functional relevance of Notch4 in breast cancer development and angiogenesis." (PMID 23601498, 2013). "However, 1 Balb/cfMMTVCZ and 2 Balb/cfMMTVSP mammary tumors had MMTV insertions within Notch4/Int3." (PMID 23131872, 2012). "In breast cancer, the overexpression of NOTCH1 and NOTCH4 in tumors suggests their role as oncogenes." (PMID 41561443, 2026). "In particular, the study demonstrated the ability of the Notch4 inhibitor RO4929097 to reverse the acquisition of resistance to tamoxifen and fulvestrant treatment in breast cancer cells dissociated from PDX after long-term treatment with antiestrogens." (PMID 39996758, 2025). "Notch4 expression increases in ECs of some mouse tumor models, including MMT-PyMT breast carcinomas and ASV-B hepatocellular carcinoma." (PMID 38984877, 2024). "In triple-negative breast cancer, NOTCH4 transcriptionally upregulated SLUG and GAS1 to maintain mesenchymal-like characteristics of breast cancer stem cells." (PMID 37386521, 2023).
breast cancer (continued). "Sun and colleagues reported a direct interaction between the ICD of NOTCH4 and SMAD3 and demonstrated that this interaction attenuated TGFβ-mediated growth inhibition of MCF-7 breast cancer cells." (PMID 36970723, 2022). "NOTCH4, on the other hand, enhances the STAT3 pathway and can be effective in amplifying breast cancer cells and reducing the effect of Tamoxifen." (PMID 35928368, 2022). "Notch4 and CDH5 are two important genes involved in EMT and the aggressive phenotype of breast cancer." (PMID 34149795, 2021). "We also investigated the possible relationship between TACC3, Notch4, and CDH5 in the proliferation of breast cancer cells." (PMID 34149795, 2021). "To verify the correlation between TACC3 and Notch4 and CDH5, we examined the RNA-seq data (N = 4,712) of breast cancer cohort in the TCGA database by using bc-GenExMinerv 4.4." (PMID 34149795, 2021). "In a single cell gene expression analysis, NOTCH4, NOTCH3 and JAG1 were upregulated in metastatic breast cancer cells compared to primary tumour cells isolated from TNBC patient-derived xenograft (PDX) models." (PMID 34295896, 2021). "Again, we observed significant upregulation of NOTCH4 in TNBC, in comparison with other two subtypes (Luminal and HER2+) of breast cancer." (PMID 32104513, 2020). "Another study also showed that in ER positive breast cancer treatment with FKBPL-based therapeutics inhibited endocrine therapy resistant stem cells via downregulating DLL4 and Notch4." (PMID 32636747, 2020). "Estradiol, while it stimulates proliferation of ER+ breast cancer cells, is a potent stabilizer of the DAXX protein and repressor of NOTCH4 and other stem cell genes thus inhibiting TICs." (PMID 32864429, 2020). "Survival analysis was used to study the relation of NOTCH4, SLUG and GAS1 with prognosis of breast cancer." (PMID 32104513, 2020). "We also confirmed the expression of NOTCH4, SLUG, GAS1 and CCND1 in different subtypes of breast cancer cell lines and observed expected expression patterns." (PMID 32104513, 2020). "Next, the localization of endogenous Notch4 was assessed in HCC1086, BT-549, Hs578T, and SUM149 breast cancer cell lines." (PMID 32123583, 2020). "In an additional study, treatment of ER+ breast cancer with tamoxifen or fulvestrant resulted in an increased BCSC population, via upregulation of Jagged-1 and Notch 4 signalling." (PMID 32575680, 2020). "For example, in breast cancer targeting HER2 activates NOTCH1 and inhibition of AKT and PI3K enhances NOTCH4 signaling." (PMID 31336602, 2019). "In support of a mechanistic role of EMT in tamoxifen resistance of breast cancer cells, over-expression of Pin-1, AKT, Nicastrin and Notch4, FoxM1, brachyury as well as modulation of several microRNAs has been reported." (PMID 26206152, 2015). "Notch1 and Notch4 expression were lower, but VEGFR2 expression was higher in stromas from TNBC compared with ER- and ER+ breast cancer stromas." (PMID 24716804, 2014). "Leptin, OB-R, Notch4, JAG1 and, IL-1R tI were detected in more than 60% of breast cancer (ER+, ER- and, TNBC)." (PMID 24716804, 2014). "Aberrant expression of the active intracellular domain of Notch4 (N4ICD) prevents differentiation and ultimately induces mammary carcinomas in mice." (PMID 23593654, 2013). "Previously Notch4/Int3 was reported to be a CIS in 2 Balb/cfMMTVC3H, 2 BR6 mammary tumors and in 43% of feral Mus musculus jyg mammary tumors." (PMID 23131872, 2012). "Studies in the human breast cancer cell lines MCF7 and MDA-MB-231 show that NOTCH1 or NOTCH4 silencing reduces tumorsphere formation and inhibits tumor growth in vivo; however, NOTCH4 suppression appears to have the greatest inhibitory effect." (PMID 22992387, 2012). "Notch1 and Notch4 can drive cell cycle progression in the absence of estrogen in ERα-positive breast cancer cells and induce the expression of cyclins A and B." (PMID 37568775, 2023).